TSPAN2 (tetraspanin 2)
Description:
May play a role in signalling in oligodendrocytes in the early stages of their terminal differentiation into myelin-forming glia and may also function in stabilizing the mature sheath.
Synonyms: Tspan-2; TSN2; FLJ12082; NET3
Tractability: Antibody: UniProt predicts a signal peptide or a membrane-spanning region; its Gene Ontology location is reachable by antibodies, with medium confidence.
Gene: Protein-coding gene on chromosome 1 (115,048,011 to 115,089,503, reverse strand). Ensembl gene ENSG00000134198.
Subcellular location: Membrane
Subcellular location (Human Protein Atlas): Nucleoplasm
Gene Ontology:
Molecular function: protein binding
Cellular component: nucleoplasm; membrane; plasma membrane; myelin sheath
Genetic constraint (gnomAD): Loss-of-function variants: 24 observed, 28.24 expected, observed/expected ratio (o/e) 0.85, 90% interval 0.61 to 1.2. The upper end of that interval is the gene's LOEUF score, 1.2, which puts it in group 5 of 6, group 1 being the genes least tolerant of losing a copy. Missense variants: 275 observed, 266.26 expected, observed/expected ratio (o/e) 1.03, 90% interval 0.94 to 1.14. Synonymous variants: 113 observed, 95.74 expected, observed/expected ratio (o/e) 1.18, 90% interval 1.01 to 1.38.
Homologues: Orthologues: dog TSPAN2 (95% identical), guinea pig TSPAN2 (95% identical), rat Tspan2 (95% identical), mouse Tspan2 (94% identical), chimpanzee TSPAN2 (90% identical), rabbit TSPAN2 (87% identical), pig TSPAN2 (86% identical), macaque TSPAN2 (68% identical), tropical clawed frog tspan2 (56% identical), zebrafish tspan2a (53% identical), zebrafish tspan2b (43% identical). Paralogues in human: CD9 (48% identical), CD81 (43% identical), TSPAN1 (30% identical), CD151 (29% identical), TSPAN5 (29% identical), TSPAN17 (29% identical), CD82 (28% identical), TSPAN4 (28% identical), TSPAN18 (27% identical), TSPAN8 (27% identical), TSPAN11 (27% identical), TSPAN14 (26% identical), and 20 more.
Diseases named in the same sentence as TSPAN2 in open-access papers:
TSPAN2 is named in the same sentence as 30 diseases in open-access papers, as found by Europe PMC text mining. Sharing a sentence is not in itself a finding about the gene and the disease. The quoted sentences say what the papers report.
migraine (12 papers, 2014 to 2024). "Meanwhile, the SNP rs2078371 maps close to the TSPAN2 gene and has been proven to have a significant association with migraine." (PMID 30258394, 2018). "A case-control study (425 patients with migraine and 425 healthy controls) in a Chinese Han population was performed to evaluate the associations between migraine and TSPAN2 via a genotype-phenotype analysis between TSPAN2 and clinical symptoms." (PMID 30258394, 2018). "Previous studies, including GWAS findings, identified the SNPs rs12134493 and rs2078371 of TSPAN2 as being associated with migraine susceptibility." (PMID 30258394, 2018). "In conclusion, we performed a replicate study to identify the associations between the TSPAN2 SNPs rs12134493 and rs2078371 and migraine in a Chinese Han population." (PMID 30258394, 2018). "Previous studies have identified significant associations of the TSPAN2 single nucleotide polymorphisms (SNPs) rs12134493 and rs2078371 with migraine in Western populations; however, these associations need to be confirmed in the Chinese Han population." (PMID 30258394, 2018). "Furthermore, the subtype analysis in this meta-analysis concluded that migraine without aura (MO) was significantly associated with seven genetic loci: near TSPAN2, TRPM8, PHACTR1, FHL5, ASTN2, FGF6, and LRP1." (PMID 39850553, 2024). "Our findings suggested that TSPAN2 is a potential susceptibility factor for migraines." (PMID 30258394, 2018). "In conclusion, the C allele of the TSPAN2 SNP rs2078371 could decrease the risk of migraine, and the T allele would increase such risks." (PMID 30258394, 2018). "In addition, we carried out further studies to see whether TSPAN2 is associated with susceptibility to migraine to provide new clinical evidence." (PMID 30258394, 2018). "Of the 25 overlapping genes/loci, 6 genes/loci were associated with more than 2 phenotypes in HPGDB (COMT, OPRD1, IL1A, IL1B, TSPAN2/NGF, GDF5), and 15 genes were associated with migraine." (PMID 37144689, 2023). "In this context, it is noted that polymorphisms in genes including TGFBR2, TSPAN2, and PRDM16 are also associated with migraine risk, underlining a potentially important role of these genes in migraine pathogenesis and therapy success in migraine." (PMID 35222013, 2021). "We further found the pathways “positive regulation of cytosolic calcium ion concentration” and “inositol phosphate-mediated signaling” and hub genes including MEF2D, TSPAN2, PHACTR1, TRPM8 and PRDM16 related to migraine susceptibility." (PMID 32046629, 2020). "In addition, TSPAN2 is highly expressed in oligodendrocyte lineage cells, and it may regulate the differentiation of oligodendrocytes into myelin-forming glia, which suggested that TSPAN2 could have an association with migraine." (PMID 30258394, 2018). "Furthermore, genetic variants related to MMP16, TGFBR2, TSPAN2, and LMP1 have been linked to therapy outcome changes with sartans in migraine." (PMID 35222013, 2021). "The presence of the tetraspanin 2 (TSPAN2) gene SNP rs12134493 tended to be associated with a lower effect of ergotamine in migraine without aura, as studied in 244 Danish individuals." (PMID 35222013, 2021). "For other hub genes for migraine, TSPAN2 is highly expressed in oligodendrocyte cell lines and may regulate the differentiation process of oligodendrocytes to myelin-forming glia." (PMID 32046629, 2020). "Genotype and allelic frequencies of the TSPAN2 SNPs in patients with different migraine subtypes." (PMID 30258394, 2018). "Whereas seven loci (i.e. near TSPAN2, TRPM8, PHACTR1, FHL5, ASTN2, near FGF6, and LRP1) were associated with migraine without aura (in a sample of 8348 cases and 139,622 controls), none were associated with migraine with aura (6332 cases vs. 144,883 controls)." (PMID 32503413, 2020). "However, up till now, the potential role of TSPAN2 and MEF2D in migraine development still remains unknown." (PMID 32046629, 2020).
migraine (continued). "Meanwhile, other SNPs such as rs2078371 (near TSPAN2) the model identified with the BIC changed from non-selective (i.e., “basic”) in the limited group to being preferentially associated with migraine characterized by sensitivity to sound in the larger samples (both pcor=0.001)." (PMID 33643179, 2020).
Stroke (5 papers, 2018 to 2022). Sudden impairment of blood flow to a part of the brain due to occlusion or rupture of an artery to the brain. "Specifically, 3 genes have been associated with atherothrombotic stroke subtype (HDAC9, CDKN (locus 9p21) and TSPAN2), 2 genes with cardioembolic stroke subtype (PITX2 and ZFHX3), and 2 genes with young strokes (ABO and MMP12)." (PMID 29321829, 2018). "In the same year, and with a sample size of 16,851 cases and 32,473 non-stroke controls, the NINDS Stroke Genetics Network (SiGN) found a new locus associated with LAS close to TSPAN2 and confirmed the previous loci ABO, HDAC9, PITX2, and ZFHX3." (PMID 35743317, 2022). "We identified colocalization signals at several established single trait loci such as TCF21, ADAMTS7, and LIPA for CAD, and NGF, FHL5, TSPAN2, and SLC24A3 for stroke." (PMID 31917787, 2020).
lung adenocarcinoma (3 papers, 2015 to 2018). A carcinoma that arises from the lung and is characterized by the presence of malignant glandular epithelial cells. "Although studies have revealed that TSPAN2 is involved in tumor metastasis and invasiveness in human lung adenocarcinomas, notably in malignancy, further studies are required." (PMID 30258394, 2018). "Thus, we provide a mechanistic entry point to unravel the effects of elevated TSPAN2 levels in cancer such as lung adenocarcinomas." (PMID 25814554, 2015).
lung carcinoma (2 papers, 2015 to 2021). "Elevated TSPAN2 levels are associated with dismal prognosis in lung cancer." (PMID 33718151, 2021). "Recently, TSPAN2 has been shown to be involved in motility and invasion in lung cancer." (PMID 25814554, 2015).
bipolar disorder (1 paper, 2023). A disorder of the brain that causes unusual shifts in mood, energy, activity levels and the ability to carry out day-to-day tasks. "Our current findings are novel in highlighting the importance of Tspan2 for Bipolar disorder in humans and represents a critical starting point for further research." (PMID 36624117, 2023).
epilepsy (1 paper, 2020). A brain disorder characterized by episodes of abnormally increased neuronal discharge resulting in transient episodes of sensory or motor neurological dysfunction, or psychic dysfunction. "Knockout of Tspan2 activates white matter astrocytes and microglia, suggesting that Tspan2 inhibits neuroinflammation, a central pathogenic process in epilepsy." (PMID 33132826, 2020). "Therefore, we speculate that KD also suppresses epileptogenesis by increasing Tspan2 and suppressing epilepsy-associated neuroinflammation." (PMID 33132826, 2020).
glioblastoma (1 paper, 2026). The most malignant astrocytic tumor (WHO grade IV). "Altered expression of TSPAN2 has been reported across glioma transcriptomic and proteomic studies, and modulation of TSPAN2 influences microglial activation and cytokine signaling, processes increasingly recognized as contributors to the glioblastoma microenvironment and treatment resistance." (PMID 41596752, 2026).
glioma (1 paper, 2026). A benign or malignant brain and spinal cord tumor that arises from glial cells (astrocytes, oligodendrocytes, ependymal cells). "Beyond their association with survival, experimental and transcriptomic studies provide evidence that CNTN2 and TSPAN2 may play active roles in glioma biology." (PMID 41596752, 2026).
hepatic disease (1 paper, 2023). "Recombinant Schistosoma mansoni Tetraspanin-2 formulated on Alhydrogel (Sm-TSP-2/Alhydrogel) is being developed to prevent intestinal and hepatic disease caused by S. mansoni." (PMID 36996185, 2023).
leukemia (1 paper, 2020). A malignant (clonal) hematologic disorder, involving hematopoietic stem cells and characterized by the presence of primitive or atypical myeloid or lymphoid cells in the bone marrow and the blood. "Although the role of TSPAN2, STAB1 and MBTPS1were not confirmed in leukemia, they were reported to be involved in the progression of the tumor metastasis." (PMID 31892991, 2020).
migraine headaches (1 paper, 2015). "The potential role of TSPAN2 in migraine headaches is unclear." (PMID 26231841, 2015).
neuroblastoma (1 paper, 2015). Neuroblastoma (NB) is the most common solid, extracranial childhood tumor. "Common genes include Jagged 1 (Jag1), Tetraspanin 2 (Tspan2), neuroblastoma, suppression of tumourigenicity 1 (Nbl1) and N-myc downstream regulated gene 2 (Ndrg2)." (PMID 25545425, 2015).
oral cancer (1 paper, 2024). "The intersection of these oral cancer-related genes with our curated list of predicted and validated let-7c-5p targets resulted in three genes of interest: HOXA1, TAGLN, and TSPAN2." (PMID 39308508, 2024).
cancer (8 papers, 2015 to 2025). A tumor composed of atypical neoplastic, often pleomorphic cells that invade other tissues. "TSPANs like CD9 (the closest TSPAN2 relative) or CD151 are associated with many stages in tumor formation or increased metastasis in various cancers." (PMID 25814554, 2015). "TSPAN2 is responsible for invasion and motility of different cancer cells and TSPAN2 interaction with CD44 is crucial for maintenance of the intracellular level of reactive oxygen species." (PMID 32507938, 2020). "PIK3R3 (p55) is one of five regulatory PI3K subunits involved in the growth response of human cancers, and previous studies have shown that it can bind to TSPAN2." (PMID 31911756, 2020). "Tetraspanin-2 has indeed reported as being involved in cancer metastasis and tumor-related angiogenesis." (PMID 31665089, 2019). "A further pathway activity study revealed that TSPAN2/4/5/9/11/18/22/25/26/28/32 were significantly associated with the activation of the epithelial-mesenchymal transition (EMT) pathway, a critical pathway for cancer cell metastasis." (PMID 37587203, 2023). "The hypothesis is that conditional pY-dependent interactions with different adaptor proteins, GRB2 or PIK3R3, respectively, may be altered in cancer, suggesting further investigation of TSPAN2 and its interactions in the transition of cells to abnormal growth." (PMID 25814554, 2015). "TSPAN2 is hypothesized to be involved in oligodendrocyte differentiation and cancer metastasis." (PMID 37550290, 2023). "Using binding assays, protein complementation and phenotypic readouts to characterize the pY-dependent interactions of TSPAN2 (tetraspanin 2) and GRB2 or PIK3R3 (p55γ), we exemplarily provide evidence that the two pY-dependent PPIs dictate cellular cancer phenotypes." (PMID 25814554, 2015).
tumor (6 papers, 2015 to 2023). "TSPAN2/13/25/29 showed low expression in normal tissues but medium to high expression in tumor tissues." (PMID 37587203, 2023). "In tumor-conditioned ECs, epigenetic silencing of Tspan2 was identified as a driver of angiogenesis corroborated by the direct angiostatic effect caused by DNA methyltransferase and histone deacetylase inhibitors-treatment." (PMID 31665089, 2019). "Finally, we used TIMER database to study the link between abundant tumor immune infiltrates (CD4+ T-cells, CD8+ T-cells, B-cell, neutrophils, macrophages, and dendritic cells) and the expression of CCR5 and TSPAN2." (PMID 33718151, 2021).
infection (2 papers, 2011 to 2023). The state of being infected such as from the introduction of a foreign agent such as serum, vaccine, antigenic substance or organism. "Recombinant S. mansoni Tetraspanin-2 (Sm-TSP-2) formulated on Alhydrogel, an aluminum hydroxide salt adjuvant, is being developed to prevent heavy infections with S. mansoni, given that morbidity is related to infection intensity." (PMID 36996185, 2023).
adenocarcinoma (1 paper, 2015). A common cancer characterized by the presence of malignant glandular cells. "Our data open up a possible function of phospho-tyrosine 124-mediated interactions related to TSPAN2's involvement in adenocarcinoma invasion and migration." (PMID 25814554, 2015).
colorectal (1 paper, 2020). "Additionally, the genes that were highly expressed in colorectal patients are TSPAN2, TSPAN5, TSPAN12, TSPAN28, TSPAN29, and TSPAN33." (PMID 32694936, 2020).
TSPAN2 also shares sentences with these, for which no sentence is quoted: atherosclerosis (1 paper); atrial fibrillation (1); bacterial infection (1); cholangiocarcinoma (1); coronary artery disease (1); fascioliasis (1); herpesvirus infections (1); ischemic stroke (1); migraine without aura (1); Photophobia (1); schistosomiasis (1); spastic ataxia (1).